STAT3 (signal transducer and activator of transcription 3)
Diseases named in the same sentence as STAT3 in open-access papers (continued):
Sharing a sentence is not in itself a finding about the gene and the disease.
cancer (continued). "However, the level of Akt3 and Stat3 between WT and Pdia4–/– cancer stroma was slightly different." (PMID 35170261, 2022). "Moreover, STAT3 pathway inhibitors are reported to be effective in cancer treatment." (PMID 35356799, 2022). "Finally, we outline more approaches to target STAT3 founded in other cancers, which may propose potential directions for further research to develop more specific STAT3 inhibitors for OSCC treatment." (PMID 36231093, 2022). "Thus, STAT3 represents an attractive therapeutic target for the treatment of human cancers." (PMID 35844184, 2022). "Hence, the establishment of a TIMP-1/IL-6 loop to increase STAT3 activity may depend on cancer type and CAF subtype." (PMID 36291767, 2022). "Interestingly, STAT3 has been found to bind to the PD-L1 promoter in cancer cells." (PMID 36230984, 2022). "Notably, microbial dysbiosis and over-activation of NF-κB, STAT3, and Wnt/β-catenin signaling pathways are contributed to cancer pathogenesis by regulating anti-tumor immune response, promoting inflammation, and inducing cancer cell proliferation and metastasis." (PMID 35794566, 2022). "Since STAT3 is the converging point of many upstream stimuli, receptors, and ligands, combining anti-STAT3 agents with other chemotherapy or immunosuppressants might offer promising ways to delay the progression of aggressive cancers." (PMID 36145523, 2022). "The STAT3 pathway could be a novel target for cancer treatment and prevention in ESCC." (PMID 36106333, 2022). "Mainly, STAT3 plays a central role in the transduction of the signal by different receptors acting as a transcription factor but it is also important in the regulation of immune system and, through these mechanisms, it can contribute to the development of cancer cells." (PMID 36012138, 2022). "Therefore, STAT3 has long been considered a therapeutic target for diseases such as cancer." (PMID 36142231, 2022). "Therefore, inhibition of STAT3 is a promising therapeutic strategy for cancer treatment." (PMID 36443287, 2022). "However, it remains unclear the signaling mechanisms that maintain the stability of DJ-1 by TrkC and activate STAT3 by DJ-1 in cancer." (PMID 36202793, 2022). "Thus, our study may provide new appealing anti-cancer strategy to inhibit the oncogenic functions of STAT3 by targeting CypB in CRC." (PMID 36266267, 2022). "Five important targets, Signal transducer and activator of transcription 3 (STAT3), Phosphatidylinositol 3-kinase alpha (PI3Kalpha), c-Kit Tyrosine Kinase (c-Kit), Protein kinase B (Akt) and Human Aurora B kinase, were selected as important proteins in cancer treatment." (PMID 36432091, 2022). "Therefore, activating STAT3 by suppressing immune exhaustion through inhibition of PD-L1 expression may be a viable strategy for cancer treatment." (PMID 35927628, 2022). "As a consequence of this, STAT3 has come to be regarded as a potentially fruitful target in DCs, and the induction of anticancer immunity that it facilitates may be made more effective by the application of targeted cancer immunotherapy." (PMID 36157880, 2022). "Furthermore, EGFR/STAT3 pathway promotes and maintains cancer stemness." (PMID 35681787, 2022). "The STAT3 pathway could serve as a novel target for ESCC cancer treatment and prevention." (PMID 36106333, 2022). "Consequently, the Pdia4/Stat3 axis increased the Vegf family in stromal cells and, in turn, assisted in creating an immunosuppressive cancer microenvironment as well as angiogenesis, leading to cancer development." (PMID 35170261, 2022).
cancer (continued). "The discovery that IL-6-activated STAT3 transcription factors form phase-separated biomolecular condensates in the cytoplasm and the nucleus provide a novel basis for targeting such STAT3 nanodroplet and condensate biochemistry in the cytoplasm and/or the nucleus for anti-cancer therapeutics." (PMID 35406728, 2022). "Therefore, JAK/STAT3 signaling pathway might play a key role in the clinical detection of CRC and it is necessary to explore whether JAK/STAT3 pathway participates in or plays an anti-cancer role." (PMID 35946886, 2022). "Furthermore, the dependence on STAT3 was differentiated following the cancer cell line." (PMID 36230984, 2022). "Moreover, exosomal glycoprotein 130 (gp130) is capable of being transferred to bone marrow-derived macrophages (BMDMs) via cancer cell-derived sEVs, activating the gp130-signal transducer and activator of transcription 3 (STAT3) signalling pathway to promote IL-6 production." (PMID 36096820, 2022). "Other miRNAs are implicated in the activation of cancer development such as miR-19 and miR-501-5p through activating wingless (WNT)/β-catenin signaling pathway, and miR-483-5p, miR-196b-5p and miR-494-3p through activating the cyclin D1, STAT3, and Notch1 signaling pathways." (PMID 35327559, 2022). "Consequently, blockade of gene regulation mediated by STAT3 could inhibit Bcl‐XL expression and induce apoptosis in cancer cells." (PMID 35356799, 2022). "In addition, STAT3 inhibition in cancer cells may stimulate the type 1 interferon response elicited by anthracyclines, resulting in an enhanced chemotherapy‐associated anticancer immune response." (PMID 35665592, 2022). "Together, these results indicate that PSY suppresses the proliferation of CRC cells by inhibiting the STAT3 signaling pathway, suggesting PSY as a potential therapeutic agent for treating CRC and 21 EtOH-Ex-enriched phytochemicals as anti-cancer drug candidates which may act by inhibiting STAT3." (PMID 36499154, 2022). "It has to be emphasized that cancer development is a multistage process that may be induced by environmental hazards, inflammatory agents, and modulators of transcription factors (e.g., NF-κB, STAT3, and AP-1) that mediate communication between cancer cells and inflammatory cells." (PMID 36142391, 2022). "Of note, in cancers associated with gammaherpesviruses, both NRF2 inhibition and NRF2 activation may represent a promising therapeutic approach, as ROS, unless they are too high, can sustain pro-survival, oncogenic pathways, such as STAT3." (PMID 36614036, 2022). "Beyond affecting cancer cell-intrinsic signaling, niclosamide can regulate signals communicated from other cell types in the tumor microenvironment such as adipocyte-mediated epithelial to mesenchymal transition through inhibition of the interleukin-6/STAT3 signaling axis." (PMID 36479072, 2022). "In addition to activating the STAT3 pathway, xenograft studies have shown that this mechanism is responsible for the induction of a cancer stem cell state in GBM cells (OLIG2, SOX2, and POU3F2 are up-regulated)) leading to higher tumorigenicity and TMZ resistance (Molecular event 28)." (PMID 36555253, 2022). "In addition, many studies have shown that AMF can block STAT3 activation in various cancers." (PMID 35237153, 2022). "However, it was demonstrated that CQ treatment may reduce STAT3 in cancer stem cells cultivated in vitro." (PMID 34299065, 2021). "In addition, the studies on molecular mechanisms revealed that MPSE or PGG could enhance the radiosensitivity of HNSCC via targeting cancer stem-like cells through attenuated STAT3 activation." (PMID 34502158, 2021). "Besides, variant rs351855‐G/A can lead to germline FGFR4 G388R substitution, subsequently expose a membrane‐proximal STAT3‐binding site and trigger STAT3 signalling cascade, which can accelerate cancer progression and also contribute to tumour‐extrinsic immune evasion." (PMID 33655556, 2021).
cancer (continued). "However, in most malignant tumors, STAT3 is abnormally activated via tyrosine phosphorylation." (PMID 33854974, 2021). "Furthermore, activated EGFR via tyrosine phosphorylation at Y1068 initiates downstream signaling pathways, resulting in signal transducer and activator of transcription 3 (STAT3) activation that directly regulates cancer cell proliferation, metastasis, and angiogenesis." (PMID 34445110, 2021). "Furthermore, an increase in STAT3 levels has been hypothesized to be a protected reaction of cancer cells to potent stressors as exposure to carbon ion irradiation." (PMID 34141616, 2021). "In addition, it has been described that AnxA1 induces STAT3 activation in cancer." (PMID 34571894, 2021). "Therefore, STAT3 should be a valuable target for cancer therapy." (PMID 33981228, 2021). "In addition, our KEGG pathways and gene ontologies studies showed that the CDK2/4/6 and STAT3 clustering PPI network were associated with pathways and processes involved in the cell cycle, DNA replication, cell communications, immune response, and cancers." (PMID 33668805, 2021). "Furthermore, STAT3 has been validated to affect cancer cell sensitivity to radiation." (PMID 34502158, 2021). "Notably, we further identified multiple reported malignancy‐related genes (e.g., MET, PIK3R1, PRKCA, PTEN, SHC1, and STAT3) upregulated in HCC272, and demonstrated that these genes were mainly enriched for cancer‐related functions, which were associated with broad drug resistance." (PMID 34105295, 2021). "In addition, SLURP-1 was shown to abolish STAT3 upregulation in cancer cells." (PMID 33815383, 2021). "LL1 could be a promising therapeutic drug candidate for cancer by inhibiting the STAT3 activation." (PMID 34059647, 2021). "Additionally, diHEP-DPA directly inhibited cancer stemness by inducing the production of reactive oxygen species (ROS), which, in turn, reduced the phosphorylation of nuclear signal transducer and activator of transcription 3 (STAT3)." (PMID 34573091, 2021). "However, STAT3 play a key role in liver inflammation and cancer." (PMID 34057016, 2021). "Therefore, STAT3 is a potentially attractive target for cancer treatment." (PMID 34291563, 2021). "However, whether RIPK4 induces EMT through the IL-6/STAT3 pathway still needs to be explored in malignant epithelial cancers, particularly in OC." (PMID 33855091, 2021). "Further investigation found that trapped cancer cells could internalize NETs via toll like receptor TLR4/9, leading to the activation of inflammatory signalling such as NFκB, MAPK/p38 and STAT3 pathway in cancer cells and thereby facilitates metastatic outgrowth." (PMID 34271947, 2021). "Of note, STAT3’s role in cancer recurrence is just beginning to unravel, and a recent study in contrast demonstrated that dormant breast DTCs residing in the BM niche remain dormant upon activation of STAT3 via the activation of leukemia inhibitory factor (LIF) receptor." (PMID 33987095, 2021). "Thus, NLRP3 is a therapeutic target to reverse canonical STAT3 mediated cancer promotion." (PMID 34531850, 2021). "STAT3 is constitutively activated in many cancers and may be oncogenic." (PMID 34760885, 2021). "Therefore, STAT3 is a newly emerging target of immunotherapies for many types of cancer." (PMID 33925645, 2021). "Although STAT3 degraders and inhibitors all target STAT3 to exert their anticancer activities, it was unclear whether the presence and abundance of STAT3 protein in cancer cells correlate with or predict cell sensitivities or responses to these STAT3‐targeting agents." (PMID 34291563, 2021).
cancer (continued). "Likewise, overexpression of the oncogene STAT3 shows that lysosomal STAT3 increases lysosomal acidification, overall suggesting a central role in controlling the lysosomal acidification axis for therapy in a wide variety of cancers." (PMID 32515674, 2021). "As a result, targeting the STAT3 signaling axis could prove to be significant for managing cancer." (PMID 33671112, 2021). "In addition, the role of HCMV in promoting STAT3 phosphorylation suggested that HCMV may participate in the occurrence and development of malignant tumors through the IL-6/JAK/STAT3 signaling pathway." (PMID 34194533, 2021). "Hence, the down-regulation of the IL-6/STAT3 signalling is critical in cancer management." (PMID 34078370, 2021). "Hence, abrogation of the STAT3 signaling pathway might represent an efficacious strategy for cancer prevention and therapy." (PMID 34277430, 2021). "In addition, activated STAT3 triggers characteristics of cancer, including angiogenesis." (PMID 34900984, 2021). "The PI3K/AKT/mTOR signaling pathway is an effective therapeutic target in PTEN-deficient cancer cells, but its inhibitors can induce resistance via feedback activation of STAT3, which provides an empirical basis for combining both PI3K/AKT/mTOR and STAT3 inhibitors." (PMID 33431808, 2021). "(2019) reported that fibroblast growth factor receptor (FGFR) inhibitor resistance in lung cancer is initially mediated by the cancer cell secretome activating STAT3 signalling; however, they also showed that this resistance could be enhanced via interactions with both fibroblasts and macrophages." (PMID 34137158, 2021). "Therefore, matrine could significantly suppress the phosphorylation levels of JAK2/STAT3 signaling pathway in cancer cells." (PMID 34642304, 2021). "Thus, we speculated that STAT3-induced inhibition of apoptosis may be involved in the survival of cancer cells after chemotherapeutic agent exposure in NSCLC." (PMID 34885780, 2021). "In addition to phosphorylation of canonical tyrosine 705 in JAK‐STAT3 (Janus kinase‐STAT3) signalling, it mediates and facilitates cancer metastasis and growth by signalling through serine 727 phosphorylation noncanonically, and in its state with no unphosphorylation." (PMID 34291563, 2021). "Moreover, other signals, such as JAK/STAT3 signaling, have roles in cancer angiogenesis." (PMID 34783299, 2021). "Numerous stimuli such as chronic inflammatory signaling, including the activation of the STAT3 and NF-κB transcription factors, may drive the stemness of CSCs in cancer tissue and enlarge their proportion within the cell population, thereby increasing the potential of metastasis." (PMID 34950252, 2021). "Therefore, selectively disrupting or blocking the intracellular signaling of oncogenes that are triggered in the STAT3-activated context may promote progress in the development of cancer treatments." (PMID 33805945, 2021). "Furthermore, previous studies have revealed that STAT3 signaling is an important signaling molecule involved in many cellular processes, including inflammation, apoptosis, and cell-cycle control, and has become a promising target for cancer treatment." (PMID 33585660, 2021). "miR-500a-3p via STAT3 pathway could promote cancer stem cells properties in HCC." (PMID 34368145, 2021). "Interestingly, ACM extract also appears to be involved in selective inhibition of cancer stem cells via STAT3 inhibition and down-regulated Src signaling, which suppresses epithelial growth factor-induced cancer stem cell conversion and inhibits tumorigenicity in vivo." (PMID 34641562, 2021). "Therefore, it would be interesting to investigate whether oxPLs regulate β-catenin pathway and JAK/STAT3 pathway in cancer cells to promote EMT and metastasis." (PMID 33806593, 2021).
cancer (continued). "However, mutations in the STAT3 gene, especially in its DNA-binding domain, diminish its ability to promote gene transcription despite normal activation of the JAK/STAT3 signaling pathway, and thereby represent a potential avenue for cancer therapy." (PMID 33535185, 2021). "Targeting the STAT3/V-ATPase axis may be a promising strategy for preventing cancer metastasis." (PMID 34234852, 2021). "Thus, the antitumor effects of compounds 2 and 5 were attributed to the suppression of STAT3 signaling, and we provided scientific evidence that compounds 2 and 5 could serve as potential agents for cancer therapy." (PMID 34638708, 2021). "Interestingly, several human cancers were found to contain constitutively activated STAT-3 protein." (PMID 34064419, 2021). "Moreover, STAT3 is reported to be an important oncogene in many malignant tumors." (PMID 33585660, 2021). "Therefore, targeting Jak2/STAT3 signaling is an important therapeutic option in cancer treatment that may help reduce angiogenesis." (PMID 34833950, 2021). "Thus, our study showed that the STAT3/CDK2/4/6 signature not only regulates immune cell infiltration but also affects the benefit for cancer patients of immune checkpoint blockade and provides a rationale for the combination of STAT3/CDK2/4/6 antagonist and immunological checkpoint inhibitors." (PMID 33668805, 2021). "Moreover, NF-κB and STAT3 also collaborate and engage in crosstalk in cancer." (PMID 33990540, 2021). "Function of mitochondria STAT3 may provide link between cancer cell metabolism and drug resistance." (PMID 33391507, 2021). "Therefore, STAT3 is a therapeutic target for cancer drug discovery." (PMID 34684783, 2021). "Indeed, B7-H3 was implicated in cancer aggressiveness since it was shown to modulate migration, invasion and adhesion to the fibronectin of various cancer cells, including melanoma cells, with the regulation of metastasis-associated proteins MMP-2, TIMP-1, TIMP-2, STAT3 and IL-8." (PMID 34572799, 2021). "Although 3FC has been shown to suppress STAT3 signaling and induce growth inhibition in cancer cell lines in an in vivo model, earlier studies have demonstrated that 3FC can also modulate functions of many cancer-promoting proteins (such as thymidine phosphorylase and DNA topoisomerase IIα)." (PMID 35053027, 2021). "In addition to controlling glucose metabolism, PKM2 also regulates hypoxia-inducible factor-1α (HIF-1α), β-catenin (β-cat), epidermal growth factor (EGFR), signal transductors, transcriptional activators 3 (STAT3), and other cancer-related factors, thereby promoting cell growth and proliferation." (PMID 33905408, 2021). "Moreover, the prospect of combining STAT3 inhibitors with other therapies has utility as evident by active clinical trials assessing the safety and efficacy of STAT3 inhibitors in combination with immunotherapies in various cancers." (PMID 34858425, 2021). "Indeed, inhibiting STAT3 activation represents a targeted therapeutic strategy to treat carcinomas." (PMID 34513827, 2021). "Furthermore, STAT3 has been shown to be constitutively active in several types of cancer, suggesting that it could be a viable therapeutic target." (PMID 32236642, 2020). "Interestingly, this score significantly correlated with many cancer hallmarks associated with immune response, including TNF-α signaling via NF-κB, IL2, and STAT5 signaling; IL6, JAK, and STAT3 signaling; inflammatory responses; IFNα response; and IFNγ response." (PMID 32988398, 2020). "Thus, understanding the functions of STAT3 is important in cancer biology." (PMID 32087696, 2020). "LDHB is largely used by cancer cells to bypass oxidative phosphorylation process to produce lactate directly from pyruvate to promote the cell proliferation, while transactivated by the key tumorigenic driver, signal transducer and activator of transcription 3 (STAT3)." (PMID 32850805, 2020). "However, the diagnosis role of p‐STAT3 in other cancers were sparely reported." (PMID 32860339, 2020).